BRAF (B-Raf proto-oncogene, serine/threonine kinase)
Diseases named in the same sentence as BRAF in open-access papers (continued):
Sharing a sentence is not in itself a finding about the gene and the disease.
melanoma (continued). "This strategy can be applied to the usage of the modern day immunotherapies such as checkpoint inhibitor immunotherapies versus targeted therapies such as BRAF/MEK inhibitors for melanoma patients before treatment." (PMID 33396862, 2020). "Since BRAF and NRAS mutations are usually mutually exclusive and clinical resistance to therapy involving these genes being a common issue in melanoma, finding new targets for treatment is crucial." (PMID 32276436, 2020). "Our study indicated that DAPT affects melanoma cells in a cell-dependent manner and that it increases the cell activity of NA8 cells (as wild-type cell in BRAF gene) but suppresses A375 cells that contain BRAF mutation." (PMID 32695658, 2020). "By looking at the signalling between melanoma cells and osteoblasts we have characterized a mechanism with the potential to provide resistance to BRAF inhibitors that is specific to the bone niche." (PMID 31323160, 2020). "Both patients with BRAF V600E-positive acral melanoma and those with heterogeneous BRAF V600E had significantly shorter melanoma-specific survival than those with BRAF V600E-negative melanoma in Kaplan–Meier analysis (p = 0.0283 and p = 0.0065, respectively)." (PMID 32143442, 2020). "We first knocked down HAT1 expression, using shRNAs in BRAF-mutant melanoma cell lines (A375 and SKMEL-28)." (PMID 32371878, 2020). "It has a higher chance of metastasizing into brain along with a shorter survival time as compared to the non-BRAF mutant melanoma." (PMID 32092958, 2020). "C32 amelanotic and COLO829 melanotic (BRAF-mutant) melanoma cell lines were used as an experimental model system." (PMID 33255659, 2020). "All the melanomas were classed into 4 group (BRAF, RAS, NF1, and Triple-WT) based on their major cancer driver genes." (PMID 32083130, 2020). "Of note, the same findings were obtained in a third additional BRAF-mutant melanoma cell line, namely WM266." (PMID 32178301, 2020). "BOP1 knockdown resulted in resistance to BRAF kinase inhibitors both in melanoma cell culture and in a melanoma mouse model." (PMID 32167616, 2020). "Of the activating RAF1-fusion melanomas, 98% (n = 39) were wild type for BRAF, NRAS, and NF1 genomic alterations (triple wild type) vs. 26% (n = 1843/7079) of the melanoma cohort without RAF1 fusion (p < 0.0001, Fisher’s exact test)." (PMID 32123303, 2020). "Mutant BRAF (V600) is the most common oncogene in melanoma, driving proliferation, survival, and tumor progression by hyper-activating MEK and ERK kinases." (PMID 31935375, 2020). "BRAF and NRAS mutations have been used as molecular biomarkers in evaluating the clinical course of melanoma." (PMID 32467670, 2020). "Since 2011 the prognosis of systemic melanoma has profoundly changed with the introduction of new targeted therapies, as BRAF inhibitors and MEK inhibitors and immunotherapy (anti-CTLA-4 and anti-PD-1)." (PMID 32575838, 2020). "Two components of the gene signature were investigated by gene silencing in BRAF/NRAS wild-type melanoma cells." (PMID 31839677, 2020). "Overall, these effects promote recognition of the tumour by the immune system and enhance anti-tumour T-cell responses in BRAF-mutant melanoma." (PMID 32645969, 2020). "Case 2 In September 2013, a 77-year-old man was diagnosed with BRAF-wild-type melanoma in the right breast region; the primary tumor and the sentinel lymph nodes in the axilla were resected." (PMID 32350591, 2020). "Our results showed that HAT1-knockdown BRAF-mutant melanoma cells were resistant to vemurafenib treatment compared with cells expressing a control NS shRNA." (PMID 32371878, 2020). "A clinical trial is ongoing in melanoma patients who showed signs of progression on BRAF-MEK inhibitor therapy (NCT02836548)." (PMID 32483452, 2020). "For the BRAF V600E mutation in melanoma, patient therapy has focused on the MAPK pathways that primarily involve BRAF and MEK." (PMID 32213878, 2020).
melanoma (continued). "BRAF and MEK inhibitors are targeted therapies approved by the FDA for the treatment of patients with BRAF-mutant melanomas." (PMID 33072757, 2020). "When the BRAF and PI3K/AKT/mTOR signaling pathways are simultaneously inhibited, the growth of drug-resistant BRAF mutated human melanoma cells can be inhibited." (PMID 32175074, 2020). "The YAP1 inhibitor Verteporfin is efficient in preclinical models of kidney fibrosis and it has been exploited as a molecular target in a pre-clinical model of melanoma, where it prevents the fibrotic phenotype induced by oncogenic BRAF inhibition." (PMID 32466585, 2020). "Combination therapy with BRAF and MEK inhibitors (MAPKi) has become standard of care for melanoma patients (approximately 50%) harboring BRAF-V600 mutations." (PMID 32933538, 2020). "We now show that diABZI negatively regulates NRF2 in C32 and SK-MEL-28 melanoma cells and sensitizes them to death induced by BRAF inhibitors." (PMID 32477956, 2020). "In the post-surgical setting, ctDNA analysis of BRAF and NRAS mutations predicted OS in 161 patients with high-risk stage II/III melanoma who underwent surgical resection followed by adjuvant bevacizumab for 1 year." (PMID 32010431, 2020). "This low glutamine-induced histone hypermethylation promoted melanoma tumour dedifferentiation and resistance to BRAF inhibitors." (PMID 32620791, 2020). "BRAF-mutant melanoma cells usually express high level of the hypoxia inducible factor (HIF) that facilitates hyperactivation of MAPK signaling and with that an increase in the proliferation rate." (PMID 33167306, 2020). "Both BRAF-associated synergistic partners for BRAF inhibitors in GDSC and TCGA data were enriched in melanoma." (PMID 33203961, 2020). "Phosphoproteomic analysis conducted on BRAF-mutant melanoma cell lines showed, after treatment with vemurafenib or after BRAF gene silencing, an increased expression of fibronectin, only in PTEN-loss contexts." (PMID 33036192, 2020). "For more insight please see Transcripts 202 and 205 of IL-6 confer resistance to Vemurafenib by reactivating the MAPK pathway in BRAF(V600E) mutant melanoma cells." (PMID 32382617, 2020). "A transcriptomic analysis of BRAF inhibitor-resistant melanoma cells showed that some transcription factors were upregulated whereas others were downregulated." (PMID 33003483, 2020). "Recent data showed that the action on symptom-free melanoma brain metastases of different immunotherapies is lower in patients previously treated with BRAF/MEK inhibitors." (PMID 31979325, 2020). "The dOPM system was applied to image a fixed multi-cellular spheroid of4434 BRAF mutant mouse melanoma cells embedded in Matrigel where actinis labelled by Alexa Fluor 488 Phalloidin." (PMID 33408991, 2020). "The treatment of melanoma cells with BRAF inhibitors reduced TERT expression and telomerase activity, suggesting that the MAPK pathway was necessary for TERT expression in these cells." (PMID 33024276, 2020). "The aim of our study was to develop reproducible three-dimensional melanoma spheroid models from BRAFV600E mutant melanoma cell lines that are sensitive and resistant to a BRAF inhibitor (BRAFi)." (PMID 32613561, 2020). "High levels of IGF-1 and FGFR-3 have been found in biopsies of melanoma patients treated with BRAF inhibitors in monotherapy or in combination with MEK inhibitors and IGF-1, and its receptor (IGF-1R) are associated with resistance to MAPK inhibitors." (PMID 33036192, 2020). "To date, BRAF mutations account for about 7% of all human solid tumors, with a high prevalence in papillary thyroid carcinomas (PTC), melanomas, colorectal cancers (CRC), and lung cancers." (PMID 33260892, 2020).
melanoma (continued). "We found that activation of p38 MAPK induces internalization and subsequent degradation of PMCA4b through the endo/lysosomal system that contributes to the low PMCA4b steady-state protein level of BRAF mutant melanoma cells." (PMID 32414111, 2020). "In summary, our study demonstrates that A20 is remarkably up-regulated in melanoma and plays an oncogenic role by simultaneously promoting tumor growth and metastasis, and rendering the acquired resistance to BRAF-targeted therapy." (PMID 32968045, 2020). "Immunohistochemistry of lung specimens was compatible with a diagnosis of malignant melanoma which was confirmed to be BRAF wild‐type." (PMID 32761808, 2020). "Among those are therapies that target the BRAF→MEK→ERK pathway, and particularly the use of BRAFV600E and MEK inhibitors to treat BRAF-mutant melanoma." (PMID 33024276, 2020). "As a proof of concept, we monitored responses of two BRAF-mutated melanoma cell lines (COLO858 and MMACSF) following exposure to a BRAF inhibitor Vemurafenib at 6 doses for a period of ~120 h." (PMID 32084135, 2020). "miRNA-204-5p, known as a tumour suppressor gene in melanoma, was associated with the CDKN2A pathway and NRAS gene and contributed to BRAF inhibitor resistance.." (PMID 32993558, 2020). "An increasing body of evidence indicate that UV radiation induce a variety of mutations in genes, such as BRAF, RAS, C-Kit, NF1 and it enhances the activation of inflammation in melanoma." (PMID 32565740, 2020). "The evolution of molecular testing in melanoma, as well as the main techniques and MPS platforms currently in use for BRAF mutation testing, have been recently reviewed." (PMID 32850962, 2020). "BRAF-mutant melanoma can escape recognition by effector T cells; for example, through low expression of melanoma differentiation antigens and by down-regulating the expression of human leucocyte antigen (HLA) class I molecules on melanoma cell surfaces." (PMID 32645969, 2020). "Our results reveal that pharmacological activation of STING by diABZI, down regulates NRF2-dependent anti-oxidative responses and potentiates cell-death in melanoma cells when used in combination with BRAF inhibitors." (PMID 32477956, 2020). "Mutations in BRAF, NRAS, and KRAS components of the MAPK/ERK signaling pathway are frequently identified in melanoma, colorectal, multiple myeloma (MM), papillary thyroid, lung, and ovarian cancers." (PMID 33198372, 2020). "Available preclinical data support the synergy between these treatment approaches, indicating such combinations provide an additional beneficial effect on the tumour microenvironment and immune response in BRAF-mutant melanoma." (PMID 32645969, 2020). "Comparative studies have suggested combination of SRS and BRAF inhibitors resulting in better outcome for BRAF-mutant melanoma patients." (PMID 32733787, 2020). "We also evaluated the correlation between concomitant genomic alterations in BRAF mutant melanomas with their clinical and pathological characteristics, as well as their potential synergistic effect on patient outcome." (PMID 32784823, 2020). "Several studies have reported specific, differently expressed genes involved in BRAF inhibitor resistance in melanoma cell lines, however most of these studies are based on monolayer cell cultures." (PMID 32613561, 2020). "JNK inhibition with the small molecule compound BI-78D3 induced apoptosis and inhibited cell growth of BRAF inhibitor-naive and resistant melanoma cells." (PMID 32252279, 2020). "Activation of PI3K/AKT pathway is one of the most recurrent resistant mechanisms for BRAF-targeted therapy, and the combination of MAPK and PI3K/AKT inhibitors becomes one of the most promising regimens for BRAF-targeted relapsed melanoma patients." (PMID 35006410, 2020). "Paradoxically, melanomas that acquire resistance to BRAF inhibition display increased sensitivity to conventional chemotherapeutic DNA-damaging agents upon drug discontinuation." (PMID 32241802, 2020).
melanoma (continued). "Functional in vitro and in vivo preclinical models of melanoma initially demonstrated the utility of small molecule BRAF inhibitors for the treatment of BRAF-mutant melanoma, providing the scientific rationale for BRAF inhibitor clinical trials." (PMID 32504051, 2020). "A significant upregulation of miR-378a-5p was also observed in malignant melanoma specimens when compared to melanoma in situ obtained from our Institute, and in melanoma cells resistant to BRAF or MEK inhibitors compared to sensitive ones." (PMID 32060259, 2020). "In the HTDS, PDXCs derived from patients harbouring a BRAF-mutant melanoma that progressed on BRAF and MEK inhibitors showed resistance to these treatments, whereas PDXCs derived from treatment-naive patients showed a marked response to these treatments." (PMID 31857724, 2020). "In BRAF V600E melanomas, loss of NF1, frequently co-occurring with BRAF and RAS alterations, allows a high level of activity of RAS-GTP and resistance to BRAF inhibitors." (PMID 32850962, 2020). "We identified pyridinyl imidazole compounds SB2020190, SB203580, and SB590885 as dual inhibitors of mutant BRAF kinase and mTOR signaling in melanoma cells." (PMID 32531927, 2020). "For trametinib, PC2 identified a pattern of differential response among trametinib-sensitive cell lines, distinguishing the responses of mostly BRAF mutant melanoma lines from other sensitive lines (largely KRAS mutant)." (PMID 32855387, 2020). "A phase II trial (NCT02631447) to determine the optimal sequencing of BRAFi + MEKi (encorafenib + binimetinib) therapy and immunomodulatory antibody (ipilimumab + nivolumab) therapy in stage III-IV metastatic BRAF V600 melanoma is ongoing." (PMID 32092958, 2020). "On the other hand, MITF loss was shown to predict early resistance to targeted therapies, including BRAF inhibitors, and seems to be a common event in acquired resistance to BRAF inhibitors in melanoma." (PMID 32605090, 2020). "Despite the success of BRAF inhibitors in melanoma, in colorectal cancer BRAF monotherapies largely fail to demonstrate clinical efficacy in BRAFV600-mutants due to feedback activation of EGFR22,23." (PMID 32487991, 2020). "For example, BRAF has a frequency above 50% in melanoma and thyroid adenocarcinoma but below 10% in all other cancer types." (PMID 32239503, 2020). "For example, in a BRAF-mutant model of melanoma, and NRAS-mutant models of melanoma, breast, and CRC, PGE2 production impairs myeloid cell activation especially the antigen-presenting ability required for T cell activation." (PMID 33092283, 2020). "NCT02858921 is a phase II trial designed to determine the optimal combination of drugs (dabrafenib, trametinib, and/or pembrolizumab) to reduce tumor size prior to surgery for patients with BRAF V600-mutated, resectable stage IIIB/C melanoma." (PMID 32260561, 2020). "In the case of BRAFV600 mutant melanoma cells treated with BRAF inhibitor, the MAPK pathway is reactivated within hours in vitro and weeks in patients." (PMID 32504051, 2020). "BRAF (v-raf murine viral oncogene homolog B1) participates in the pathological mechanism of 7% of human neoplasms, especially in melanoma, colorectal, thyroid, and lung cancers." (PMID 33489866, 2020). "In melanomas, mutant BRAF aberrantly activates the pathway downstream of Ras, thus bypassing this feedback loop." (PMID 33291749, 2020). "Various trials with metformin plus BRAF inhibitor combinations are also ongoing for numerous tumour types, including melanoma (NCT01638676, NCT02143050)." (PMID 33092283, 2020). "Application of ScRNA-seq to patient-derived melanoma minimal residual disease (MRD) of BRAF mutant xenotransplantation identified up to four different drug-resistant transcriptional states." (PMID 33614479, 2020). "Recently, prospective data about the efficacy of BRAF/MEK inhibitors’ associations, specifically in patients with stage IV melanoma and brain involvement, have been published." (PMID 32575838, 2020).
melanoma (continued). "The second most common mutation is BRAFV600K (substituting valine for lysine), which accounts for 5%–6% of BRAF-mutant melanomas." (PMID 32054078, 2020). "BRAF inhibitors have been shown to rapidly suppress melanoma growth and control the malignancy in a large proportion of patients." (PMID 32645969, 2020). "NGFRhi cells are associated with intrinsic cross-resistance to T effector cells recognizing melanoma tumor antigens unrelated to differentiation, as well as with resistance to other clinically relevant therapies, including combinatorial BRAF + MEK inhibition." (PMID 32770055, 2020). "To evaluate Siah2 function in the tumor environment, we injected cells of the BRAF-mutant melanoma line YUMMER1.7 into syngeneic wild-type (WT) or Siah2−/− mice." (PMID 31911617, 2020). "Since the development of immune checkpoint blockade and BRAF inhibition approaches, melanoma therapy has changed." (PMID 32455577, 2020). "First generation BRAF inhibitors including dabrafenib and vemurafenib have shown excellent results in melanoma patients harboring BRAF p.V600E and are now being investigated for their utility in pLGG." (PMID 32164789, 2020). "The microenvironment of BRAF-mutant melanomas can also inhibit effector T-cell functions; for example, by promoting the accumulation of regulatory T cells and myeloid-derived suppressor cells (MDSCs)." (PMID 32645969, 2020). "Phosphoproteomics and genomics tools are used to identify drug targets that can sensitize melanoma cells to BRAF inhibition." (PMID 32466585, 2020). "In the era of precision medicine, it is important to characterize melanoma tumors through molecular subtypes and to identify targeted therapies that are best suited for these subtypes—BRAF, RAS, NF1, and triple wild-type." (PMID 33256089, 2020). "A recent study suggested that COX2/PGE2 expression depends on the activation of the pathway in a BRAF mutant melanoma cell line established from a genetically engineered mouse model." (PMID 32385388, 2020). "Concluding, we show, for the first time, on a nation-wide scale and with real-life data that the frequency of a BRAF V600 mutation declines with age, whereas the frequency of an NRAS mutation increases with age in patients with advanced melanoma." (PMID 32726988, 2020). "By using preclinical model, it was proven that EGFR inhibition enhanced the antitumor effect of vemurafenib in BRAF-mutant human melanoma." (PMID 32613561, 2020). "While inhibitors targeting mutant BRAF proteins can induce melanoma regression, many tumors become resistant to these agents, possibly owing to immunological effects of BRAF inhibitor therapy." (PMID 31702822, 2020). "The repressed Wnt signaling makes melanoma cells more sensitive to oxidative stress and drive resistance to BRAF inhibitors." (PMID 33373316, 2020). "It was previously shown that Dabrafenib/Everolimus combination was effective in melanoma cell lines to bypass the induction of resistance to BRAF inhibitors." (PMID 33202906, 2020). "Our results show evidence that glutamine supplementation can slow growth in melanoma tumours with different BRAF status by inhibiting epigenetically activated oncogenic pathways." (PMID 32620791, 2020). "In another combination study, the resistance in melanoma patients following the use of the Hsp90 inhibitor XL888 with the BRAF inhibitor vemurafenib was reverted by the use of dinaciclib as a CDK2 inhibitor." (PMID 32397330, 2020). "We interrogated plasma from 38 melanoma patients identified as having clinically diagnosed treatment resistance after initial response to BRAF inhibitor monotherapy or BRAF/MEK inhibitor combination." (PMID 33216826, 2020). "Melanoma models with an acquired resistance to BRAF inhibitors, mostly to vemurafenib, became a model to study the mechanisms of drug resistance." (PMID 33091721, 2020). "COX2 knockdown by small interfering RNA (siCOX2) reduced COX2 expression levels and enhanced melanoma cell sensitivity to BRAF/MEKi." (PMID 32967672, 2020).